AR (androgen receptor)
Diseases named in the same sentence as AR in open-access papers (continued):
Sharing a sentence is not in itself a finding about the gene and the disease.
prostate carcinoma (continued). "Gene fusions of AR-regulated promoter regions with regions encoding members of the ETS (erythroblast transformation-specific) family of transcription factors are found in 40-60% of localized cases of prostate cancer." (PMID 35004302, 2021). "Androgen receptor (AR) signaling is a hallmark of prostate cancer (PC)." (PMID 33921329, 2021). "Here, we provided the evidence to show that pre-mRNA processing factor 6 (PRPF6) acts as a key regulator for action of both AR full length (AR-FL) and AR variant 7 (AR-V7), thereby participating in the enhancement of AR-FL and AR-V7-induced transactivation in prostate cancer." (PMID 33390843, 2021). "In addition, the mutations in β-catenin, which intertwines with the androgen receptor pathway, are responsible for prostate cancer." (PMID 35201496, 2021). "Aggressive variants of prostate cancer are increasingly recognized in the clinic, probably as consequence of a greater survival and the pressure of the new hormonal treatments on the androgen receptor (AR)." (PMID 33625671, 2021). "Furthermore, in addition to activating wild type androgen receptor, spironolactone has been observed to activate cells with point-variant androgen receptor that are commonly encountered in individuals with resistant prostate cancer." (PMID 34094953, 2021). "Importantly, AR activity that was restored in enzalutamide-resistant prostate cancer cells was associated with increased MED1 pT1457 and demonstrated continued sensitivity to THZ1." (PMID 33384381, 2021). "For example, the expression of a majority of androgen receptor (AR) splice variants other than the full-length AR variant remains unclear in prostate cancer progression." (PMID 33917241, 2021). "Interestingly, the length of polymorphic CAG nucleotides repeats is associated with the prostate cancer pathophysiology, as shorter CAG repeats inversely correlate to androgen receptor expression and subsequently increase the risk of prostate cancer." (PMID 33179220, 2021). "In addition to its repressor function, LSD1 is implicated in prostate cancer as a coactivator of AR signaling." (PMID 32946061, 2021). "Although prostate cancer can be stabilized or regressed by androgen deprivation therapy, reactivation of AR by overexpression, point mutation, alternative splicing and other ligand-independent manners ultimately lead to incurable castration-resistant prostate cancer (CRPC)." (PMID 33621955, 2021). "Further, high expression of ACE2 in the male urogenital system organs, including the prostate, and the overexpression of androgen receptor-regulated TMPRSS2 in prostate cancer patients, could increase their susceptibility to SARS-CoV-2 87-89." (PMID 33391502, 2021). "Finally, Onecut2 is another transcription factor involved in cellular differentiation that has been recently associated with lethal prostate cancer and the downregulation of the AR transcriptional program." (PMID 33420371, 2021). "AR has itself been implicated as a key regulator of glucose metabolism in prostate cancer cells." (PMID 32427840, 2020). "In addition, niclosamide was identified as a potent androgen receptor splice variant 7 (AR-V7) inhibitor in prostate cancer cells." (PMID 32824865, 2020). "Because AR signaling is a hallmark of prostate cancer progression, we also investigated whether AR-regulated ASE is associated with the progression of disease." (PMID 32820253, 2020). "Similarly, FOXP1 is associated with HIFs and androgen receptor (AR) in prostate cancer and downregulates AR-induced transcriptional activities and histone modifications in enhancer regions." (PMID 32552834, 2020). "Androgens, which are linked to the development of prostate cancer, may act by repressing Cx43 expression through androgen receptor pathway." (PMID 33081404, 2020).
prostate carcinoma (continued). "In prostate cancer cells, overexpression of hnRNPA1 was associated with increased levels of the androgen receptor splice variant AR-V7, which is constitutively active even in the absence of androgens and has been implicated in the development of the castration-resistant phenotype." (PMID 32417965, 2020). "Since dysregulation of AR signaling is the hallmark of prostate cancer progression, we hypothesized that ASE of functionally relevant genes would be associated with the progression of disease." (PMID 32820253, 2020). "Prostate cancers with castration resistance particularly, constitutes of many oncogenic mutations in AR such as high levels of expression, augmented copy number, alterations that affect specificity of ligand, and high level of enzyme activity involving antigen synthesis." (PMID 32055737, 2020). "Alternatively, an optimized GBM CTC enrichment protocol may allow to successfully detect EGFRvIII transcripts in CTC samples, comparable to androgen receptor variant 7 (AR-V7) analysis in prostate cancer." (PMID 32650387, 2020). "Prostate cancer non-coding RNA 1, a lncRNA transcribed from 8q24, participates in the carcinogenesis of prostate cancer (PCa) by activating androgen receptor (AR); in addition, polymorphisms of the lncRNA PRNCR1 were noted in many cancers, including colorectal cancer, prostate cancer, and GC." (PMID 32117633, 2020). "Furthermore, leveraging publicly available transcriptome data of primary-site samples from patients with prostate cancer at various stages of progression, we found a subset of AR-driven splicing events that are associated with progression of prostate cancer." (PMID 32820253, 2020). "Traditional kava, alone or combined with sea hibiscus, displayed anticancer activity against breast and colon cancer cells and reduced prostate tumor growth in association with enhanced androgen receptor (AR) protein degradation in patient-derived prostate cancer xenograft models." (PMID 33027883, 2020). "This evidence raises the possibility that AR-dependent and AR-independent circadianfunctions contribute to the prostate gland physiology, by opening a new connectionto environmental factors, knowingly significant in prostate cancer risk andincidence." (PMID 32159609, 2020). "Similarly, prostate cancer has also been thought to be linked to KDM1A due to KDM1A-mediated transcriptional regulation of AR, and KDM1A inhibition decreases prostate cancer proliferation." (PMID 33029224, 2020). "As a risk factor for prostate cancer, AR has been targeted in clinical treatment for many years." (PMID 33343635, 2020). "Post-translational modifications of α-tubulin have been shown to be associated with prostate cancer progression, with loss of acetylated α-tubulin a common feature in AR-negative castrate-resistant cell lines, suggesting a link between AR and acetylation of α-tubulin in prostate cancer." (PMID 33260953, 2020). "Evolution of mCRPC tumors may lead to an Androgen Receptor (AR) independent phenotype and loss of prostate cancer markers such as prostate-specific antigen (PSA) expression." (PMID 33109268, 2020). "In addition, we showed colocalization of HOXC4 and HOXC6 at HOXB13 sites that are also bound by FOXA1 and AR, which have been previously linked to regulation of prostate cancer cell proliferation." (PMID 32012197, 2020). "The question remains as to whether the involvement of certain pathways in AR- prostate cancers make them more or less susceptible to HDAC inhibitors." (PMID 32019149, 2020). "Because it is well-established that AR is critical for the growth of prostate cancer, and the loss of AR expression in tumor cells inhibits tumor growth, we determined whether GSA0932 affects tumor cell proliferation." (PMID 32477465, 2020).
prostate carcinoma (continued). "Recent work finds that CTCF binding sites are located at the prostate cancer-specific topologically associating domains boundaries for AR loci both in normal and cancer cells which we speculate in human tumor samples may alter expression." (PMID 32503656, 2020). "Dysregulation of androgen and AR signaling is directly associated with prostate cancer." (PMID 32641750, 2020). "Furthermore, by integrating transcriptomic data from in vitro experiments and in prostate cancer patients, we found that a significant number of AR-regulated splicing events are associated with tumor progression." (PMID 32820253, 2020). "Furthermore, it causes the suppression of androgen receptor expression and E2F-1 that is essential for the proliferation and viability of androgen-sensitive and androgen-independent prostate cancer cells." (PMID 33202681, 2020). "The BRACHYURY protein level in the nucleus of primary prostate cancer cells is statistically associated with the presence of AR, and the enhanced AR expression in the nucleus may be activated by BRACHYURY protein." (PMID 32695672, 2020). "AR mutations and polymorphisms have been extensively studied in prostate cancer and infertility." (PMID 33243086, 2020). "The androgen receptor splicing variant 7 (ARv7) that lacks the ligand-binding domain is increasingly considered as a key player leading to enzalutamide (Enz) resistance in patients with prostate cancer (PCa)." (PMID 32978369, 2020). "As a result, the suppression of AR in CAFs may potentially exacerbate the epithelial-mesenchymal transition and metastasis of prostate cancer, underpinning the association of AR loss in CAFs with adverse clinical outcomes in prostate cancer progression." (PMID 30925918, 2019). "Indeed, there is evidence that increased transcriptional activity of AR with shorter polyQ tracts corresponds to an increased risk of prostate cancer." (PMID 31686397, 2019). "Consequently, there is an urgent need to develop agents that can target both the full‐length and the splice variants of AR for more effective treatment of prostate cancer." (PMID 30905075, 2019). "Our results show that Andrographolide can restrain proliferation and stimulate apoptosis in aggressive prostate cancer cells specifically in androgen insensitive (AI) cell (PC3) since cancer cells that undergoes androgen receptor (AR) activation can cause proliferation and block apoptosis." (PMID 30800220, 2019). "SALV-ENZA is among the first phase II placebo-controlled double-blinded randomized studies to test SRT in combination with a next generation anti-androgen receptor antagonist in men with contemporary high-risk recurrent prostate cancer after radical prostatectomy." (PMID 31196032, 2019). "The heterogeneity in AR expression or activity suggest that AR deficiency may be proposed as a potential way in which prostate cancer cells escape androgen deprivation therapy, with compensatory signaling pathways activated concomitantly." (PMID 31761786, 2019). "Our finding that TLE3 loss, in conjunction with AR inhibition, leads to GR upregulation provides deeper insight into the epigenetic regulation of the GR locus in prostate cancer cells and supports the previously undescribed role of TLE3 in conferring enzalutamide sensitivity via GR." (PMID 31855178, 2019). "AR-v7, a constitutively activated splice variant of the androgen receptor (AR), was involved in disease progression and poor outcome upon AR-targeted therapies in castration-resistant prostate cancer patients." (PMID 31134126, 2019). "AR controls the growth of the prostate gland, and much evidence from preclinical and clinical studies has shown that multiple androgen/AR signaling pathways implicated throughout the various stages of prostate cancer." (PMID 30935141, 2019).
prostate carcinoma (continued). "Indeed, recent studies have established that the same Hsp70-targeted small molecules promote clearance of an AR splice variant that is associated with prostate cancer and lacks the C-terminal LBD13." (PMID 31395886, 2019). "Previous studies found that PRNCR1 plays a vital role in the development of prostate cancer predisposition and it might be pivotal in prostate cancer progression by modifying androgen receptor (AR) function." (PMID 31487296, 2019). "In addition, CWP232291 suppressed the expression of β-catenin by affecting WNT-dependent transcriptional activity, and downregulated AR and its splice variants in prostate cancer cells." (PMID 31387608, 2019). "Moreover, the fact that mutations in the hinge region are associated with prostate cancer and increase AR transcriptional activity supports the notion that the hinge region plays a key regulatory (predominantly inhibitory) role in AR activity." (PMID 31686397, 2019). "However, prostate cancer treatment with AR antagonists can also acquire resistance through AR mutations, such as AR splice variants and gene amplification." (PMID 31504033, 2019). "These functions of RNA-binding proteins could be effective for enhancement of the expressions of prostate cancer-associated genes, such as full-length AR and AR-V7." (PMID 30939845, 2019). "Besides the AR, estrogens and their receptors have also been implicated in prostate cancer initiation and progression but the translation into a potential therapeutic strategy still remains challenging." (PMID 31284411, 2019). "In addition, HNRNPH1 transcripts negatively regulated by miR-212 were associated with the expression of AR and AR-V7 in prostate cancer cells." (PMID 30939845, 2019). "Prostate cancer has traditionally been seen as an aging-associated, low mutational load tumor with a tendency for genomic rearrangements and a particular dependency on the activity of the androgen receptor (AR)." (PMID 29888169, 2018). "Deficiency of proteostasis and lack of proteasome activity in enzalutamide and abiraterone-resistant prostate cancer might trigger overexpression of onco-proteins, such as AR and its variants through an inability of protein clearance." (PMID 30446660, 2018). "This may involve non genomic actions as has been demonstrated in prostate cancer through AR filamin A association and stromal cells." (PMID 30416486, 2018). "This makes HSP90 inhibition irrelevant in the treatment of AR variant dominated prostate cancer." (PMID 30446660, 2018). "Thus, it is important to identify a common target to inhibit both AKT‐mTORC1 and AR signaling in SPOP‐mutated prostate cancer." (PMID 29523594, 2018). "However, the effect is limiting, and prostate cancer circumvents these agents in various ways, including via AR variants and the de novo production of androgen by itself." (PMID 29568400, 2018). "Overexpression of AR’s wild-type form in mouse prostate epithelium (under the probasin promoter) is sufficient to cause the type of neoplastic abnormality that is associated with early development of prostate cancer—prostate intraepithelial neoplasia (PIN)." (PMID 29921791, 2018). "A provocative new finding by Zuber and colleagues with implications in risk assessment shows that tissue-specific SNPs in super-enhancer sequence bound by BRD4 are significantly associated with increased prostate cancer risk and show better enrichment for risk loci than AR." (PMID 29888169, 2018). "There are many coregulator and AR protein interactors that have been identified in prostate cancer which are also expressed and implicated in many functions in breast cancer however there is little experimental evidence on the role of these proteins in breast cancer subtypes." (PMID 30416486, 2018).
prostate carcinoma (continued). "Xu and colleagues demonstrated that EZH2 acts as a coactivator of androgen receptor-associated complexes to support castration-resistant prostate cancer (CRPC) growth, suggesting novel combination therapies for the treatment of metastatic, hormone-refractory prostate cancer." (PMID 29556394, 2018). "Also, high nuclear RelA, together with high nuclear AR expression, is associated with poor prostate cancer outcome, indicating the existence of other relevant NF-κB/AR interactions." (PMID 30158439, 2018). "In the present study, we determined that AR variants are not only generated through mRNA splicing but also through protein stabilization via protein ubiquitin proteasome alteration in drug-resistant prostate cancer." (PMID 30446660, 2018). "We next sought to investigate whether the hormone-insensitive growth phenotype induced by ectopic TLX overexpression in prostate cancer cells could be associated with disturbance on AR signaling." (PMID 29555975, 2018). "Prostate cancer drug resistance is predominantly driven by AR mutations." (PMID 29867496, 2018). "Examples of androgen-independent prostate cancer mechanisms include promiscuous AR, hypersensitive AR, splice variant AR, outlaw pathways (e.g., insulin growth factor 1), bypass pathways (e.g., receptor tyrosine kinases), lurker cell pathways, and steroidogenesis." (PMID 30241348, 2018). "In addition, silencing of IKKα reduces androgen receptor activity and gene expression, providing evidence that IKKα is associated with prostate cancer growth." (PMID 30347849, 2018). "Moreover, emodin, a natural compound present in Japanese knotweed and rhubarb, is known to induce AR protein degradation by increasing the association between AR and Mdm2, and also to suppress prostate cancer growth in both in vitro and in vivo models." (PMID 29707137, 2018). "However, BPA acts either on AR or on its mutated variants in a dose-dependent manner by eliciting different effects on prostate cancer (PCa) cells." (PMID 29383186, 2017). "It has also been associated with several anti-cancer mechanisms of action in prostate cancer including inhibition of complex 1, lipogenesis, decreases of cyclin D1, down-regulation of the insulin-like growth factor 1 receptor and AR downregulation." (PMID 28151974, 2017). "Thus, the study of AR signaling pathways and their collaborative factors will facilitate greater understanding of the mechanisms underlying the progression of advanced prostate cancer as well as the development of novel drugs." (PMID 28264478, 2017). "It is very important to understand whether and how Cao2+ regulates the migration of AR-deficient prostate cancer cells and whether Ca2+ or Ca2+-mediated signaling plays a role in the development of castrate-resistance prostate cancer (CRPC)." (PMID 27206800, 2017). "Occupational and ambient exposure to pesticides, interacting with free testosterone bioavailability and its androgen receptor (AR) binding, might be present an association to risk of prostate cancer manifestation." (PMID 29064461, 2017). "The authors suggested there might be a specific pattern of expression of the AR associated with hereditary prostate cancer." (PMID 28255369, 2017). "AR remains important in the development and progression of prostate cancer, and the majority of androgen‐independent or hormone‐refractory prostate cancers express AR, which in part is associated with the extensive re‐programming of its transcriptional activity." (PMID 28252832, 2017). "Evidence that AR CAG repeat length is associated with prostate cancer risk remains controversial." (PMID 28039468, 2017). "Finally, GPRC6A mediates the non-genomic, rapid signaling responses to testosterone, leading to activation of PI3K/Akt pathways that are implicated in androgen receptor (AR)-independent progression and therapeutic resistance of prostate cancer." (PMID 28659174, 2017).